HLA-G (major histocompatibility complex, class I, G)
Diseases named in the same sentence as HLA-G in open-access papers (continued):
Sharing a sentence is not in itself a finding about the gene and the disease.
graft versus host disease (6 papers, 2011 to 2025). An immune system disorder that occurs after allogeneic hematopoietic stem cell transplant and is a reaction of donor immune cells against host tissues. "Low levels of HLA-G are associated with a higher incidence of graft versus host disease, while higher levels of HLA-G are consistent with reduced transplant rejection." (PMID 29259248, 2017). "polymorphism in the HLA-G gene and occurrence of graft-versus-host disease has been studied in bone marrow transplantation and other complications in solid organ transplantation." (PMID 24591768, 2014). "In the setting of stem cell transplantation, the application of HLA-G positive extracellular vesicles drastically improved therapy-refractory graft-versus-host disease." (PMID 41562090, 2025). "Taking these into account, it could be hypothesized that hypomethylating agents-induced CD4+HLA-G+FOXP3-T cells in vitro would be adoptive cellular immunotherapy against acute graft-versus-host disease." (PMID 33709198, 2021). "Because of their hypoimmunogenicity and their potential to create an immunosuppressive local microenvironment through the production of TGF-β, PGE-2, and HLA-G molecules, BM-MSC are successfully employed to prevent graft-versus-host disease (GvHD)." (PMID 21625521, 2011).
lymph node metastasis (6 papers, 2020 to 2024). "PD-L2 was associated with T stage, lymph node metastasis, and clinical staging, while in survival analysis, PD-L2 and HLA-G were associated with a shorter survival." (PMID 38954689, 2024). "In summary, our meta-analysis showed that HLA-G expression was associated with lymph node metastasis and poor OS in CRC patients, yet the bioinformatics analysis showed that the prognosis of HLA-G was inconsistent." (PMID 37875821, 2023). "The outcome showed that high HLA-G expression was strongly linked to lymph node metastasis (HR = 1.20, 95% CI = 1.04–1.38, P = 0.010)." (PMID 37875821, 2023). "HLA-G expression was associated with an increased occurrence of lymph node metastasis and capsular invasion.HLA-G could have an independent prognostic value, principally for tumor recurrence." (PMID 33425752, 2020). "HLA-G is suggestive of tumor progression and recurrence as denoted by the positive correlation between HLA-G high-expression and advanced stage, distant metastasis, lymph node metastasis, and higher recurrence rates." (PMID 38310272, 2024). "It was obvious that HLA-G expression was significantly correlated with lymph node metastasis." (PMID 37875821, 2023). "Our results revealed that in samples with higher counts of EpCAM+ tumor cells, the expression of HLA-G, ILT-2, ILT-4, and PD-L1 was significantly related to distant lymph node metastasis, advanced disease stage, and shorter patient survival." (PMID 34054869, 2021).
pemphigus vulgaris (6 papers, 2009 to 2023). Pemphigus is a group of chronic autoimmune skin diseases characterized by blister formations on the outer layer of the skin and the mucous membranes. "Skin tissue sections from pemphigus vulgaris (PV) patients express detectable HLA-G molecules at both transcriptional and translational levels, while control sections present only HLA-G transcription." (PMID 25477881, 2014).
thyroid cancer (6 papers, 2019 to 2024). "This is in contrast with increased surface HLA-G expression on thyroid cancer tissue." (PMID 33353014, 2020). "Generally, the median HLA-G mRNA expression was elevated 2-fold to 10-fold compared with matched healthy tissues, but the differences only reached significance in kidney renal clear cell carcinoma, kidney renal papillary cell carcinoma, pancreatic ductal adenocarcinoma, and thyroid cancer." (PMID 34663641, 2021). "Inconsistently, HLA-G expression did not correlate with disease stage in thyroid cancer." (PMID 38310272, 2024).
breast tumors (5 papers, 2013 to 2023). "Based on the tolerogenic functions of breast tumors, we investigated possible associations between the expression of HLA class Ia, class Ib (HLA-G and HLA-E), and class II (HLA-DQ and HLA-DR) in breast tissue." (PMID 24363939, 2013). "Each of the boxplots corresponding to the 13 datasets show a similar pattern, indicating an increased HLA-G expression in breast tumors with a high expression of ICR genes (representative plots are shown inFigure 3B)." (PMID 29527288, 2017). "Concerning its role in tumor immunity, it may be of interest to investigate whether HLA-G expression is elevated in breast tumors of specific immune phenotypes." (PMID 29527288, 2017). "HLA-G expression in tumor cells has been identified as another mediator of trastuzumab resistance, which, when coupled to the HLA-G/KIR2DL4 interaction, enhances the vulnerability of HER2+ breast tumors to trastuzumab treatment in vivo." (PMID 36982282, 2023).
cervical intraepithelial neoplasia (5 papers, 2014 to 2025). "In the same cohort, the HLA-G*01:01:02, HLA-G*01:04:01 and HLA-G*01:06 alleles were related to high-grade cervical intraepithelial neoplasia (HG-CIN)." (PMID 32670296, 2020). "It was previously reported that the expression of HLA-G in cervical intraepithelial neoplasia (CIN) with HPV16/18 infection was significantly higher than that in CIN without HPV infection, and the sHLA-G plasma level was significantly higher in CIN and SCC patients." (PMID 36618382, 2022).
esophageal cancer (5 papers, 2015 to 2022). A primary or metastatic malignant neoplasm involving the esophagus. "Further, individuals carrying the 14bp DEL/DEL and +3142C/C genotypes (DEL/C haplotype, which combines HLA-G-enhancing variants) had a 2.82-fold increased risk of esophageal cancer compared with individuals carrying the INS/C haplotype (p=0.04)." (PMID 35154112, 2022). "In summary, HLA-G expression in breast, gastric, hepatocellular and esophageal carcinoma patients was associated with significantly poor clinical outcome." (PMID 34361031, 2021). "Tumour HLA-G expression was significantly associated with poor clinical patient outcome in the majority of studies regarding breast, gastric, hepatocellular and esophageal carcinomas." (PMID 34361031, 2021). "Similarly, intratumor heterogeneity of HLA-G expression was also found in case-matched esophageal cancer blocks." (PMID 33329527, 2020). "Hence, HLA-G is a potential predictive biomarker of esophageal cancer, and the modification of HLA-G transcription or expression may be of benefit in the prevention and treatment of this type of cancer." (PMID 35154112, 2022). "Our results revealed that, in addition to the frequently observed inter-tumor heterogeneity, intratumor heterogeneous expression of HLA-G is common in different areas within a tumor in CRC and esophageal cancer samples included in this study." (PMID 33329527, 2020).
Ewing sarcoma (5 papers, 2018 to 2023). A small round cell tumor that lacks morphologic, immunohistochemical, and electron microscopic evidence of neuroectodermal differentiation. "Of note, HLA-G expression is induced by IFNγ in Ewing sarcoma cell lines, and is detected in a majority of tumor biopsies on both tumor and infiltrating myeloid cells." (PMID 38318504, 2023). "Here, we studied the capacity of two nonclassical HLA molecules with known immunosuppressive function, HLA-G and HLA-E, to prevent antigen-specific immune effector functions of gene-engineered T cells against Ewing sarcoma." (PMID 34201079, 2021). "In one cell line, TC-32, IFN-γ pretreatment induced secretion of HLA-G1/G5, proving principle that at least individual Ewing sarcomas can secrete soluble HLA-G under inflammatory conditions." (PMID 29464090, 2018). "Moreover, as previously shown for HLA-G, HLA-E was detected in a high proportion of human Ewing sarcoma biopsies." (PMID 34201079, 2021). "Accordingly, an up-regulation of CD85j expression, a ligand of HLA-G, was observed on GD2 CAR-NK cells and parental activated NK cells upon co-culture with Ewing sarcoma cell lines." (PMID 32707982, 2020). "We conclude that blockade of HLA-G and HLA-E immune checkpoints is not a promising strategy for enhancing T cell therapies in Ewing sarcoma." (PMID 34201079, 2021). "Based on our finding that Ewing sarcomas (EwS) respond to chimeric antigen receptor (CAR) gene-modified effector cells through upregulation of human leukocyte antigen G (HLA-G), we hypothesized that nonclassical HLA molecules, HLA-G and HLA-E, contribute to immune escape of EwS." (PMID 34201079, 2021).
human papillomavirus infection (5 papers, 2020 to 2024). "Two genes, HLA-G and MAML2, were also significantly upregulated in the Human papillomavirus infection pathway." (PMID 38427106, 2024). "KEGG pathway visualization showed that UCKL1 and GSTT1 were upregulated in the drug metabolism pathway, and HLA-G and MAML2 were significantly upregulated in the human papillomavirus infection pathway." (PMID 38427106, 2024).
liver fibrosis (5 papers, 2017 to 2022). "We previously demonstrated that HLA-G is expressed by mast cells that are associated with the area of hepatitis C virus-induced liver fibrosis." (PMID 34830373, 2021). "We previously demonstrated that mast cells expressing HLA-G are associated with regions of hepatitis C virus-induced liver fibrosis." (PMID 34830373, 2021). "The number of HLA-G+ mast cells is significantly associated with the areas of connective tissue and liver fibrosis located close to the hepatic arteries, veins and bile ducts of the portal tracts." (PMID 32983083, 2020). "We investigated whether HLA-G can be expressed by mast cells associated with liver fibrosis from another etiology or fibrosis in another organ by studying 41 cases of alcohol-induced liver cirrhosis, 10 of IPF, and 10 of renal fibrosis." (PMID 34830373, 2021). "In conclusion, HLA-G+ mast cells exist in the liver fibrosis region, and HLA-G+ mast cells have a protective effect on inflammation and liver fibrosis." (PMID 36176778, 2022). "As in hepatitis C virus-induced liver fibrosis, we found half of the HLA-G+ cells in alcohol-induced cirrhosis to be mast cells and only 34% of mast cells expressed HLA-G, with high individual variability shown by the standard deviation." (PMID 34830373, 2021). "In agreement, the levels of HLA-G activation positively correlate with the amount of mast cell activation and liver fibrosis." (PMID 28769934, 2017). "In addition, they identified the cell type for the first time that expressed HLA-G as mast cells, and HLA-G was expressed by mast cells in liver fibrosis areas of HCV-infected patients." (PMID 36176778, 2022). "Therefore, Mast cells play a beneficially anti-fibrotic role in liver fibrosis through HLA-G-mediated reduction of type I collagen." (PMID 36176778, 2022). "HLA-G+ CD117− mast cell tryptase HLA-G+ CD117− HLA-G+ CD117− mast-cell tryptase+, and HLA-G+ CD117+ mast-cell tryptase+ cells were counted in three representative cases of liver fibrosis using HALO software with the appropriate algorithm." (PMID 34830373, 2021). "Then, HLA-G+ infiltrating mast cells promote HSC proliferation that, in turn, induces liver fibrosis." (PMID 32983083, 2020). "It is possible that the interaction of HLA-G with IL-T2 on mast cells creates an autocrine loop, and the immune response against HCV-induces liver fibrosis via hepatic stellate cells." (PMID 28769934, 2017).
Obesity (5 papers, 2020 to 2025). Accumulation of substantial excess body fat. "Both HLA-G 14bp and +3142G/G show associations with obesity post kidney transplantation." (PMID 35769475, 2022). "Additionally, researchers found that HLA-G is directly related to IL-6, which is involved in the inflammation associated with the course of obesity and type 2 diabetes." (PMID 34948145, 2021). "This novel association could add new elements to the study of obesity susceptibility factors and to the knowledge of the role and functions of HLA-G molecules in diseases and transplantation." (PMID 32228494, 2020). "Obesity and T2DM are characterized by low-grade inflammation, and a relationship seems to exist between HLA-G, obesity, and T2DM: in a study of HLA-G production in T2DM, sHLA-G was associated with higher BMI, cholesterol and blood pressure." (PMID 32228494, 2020).
Papillary Thyroid Carcinoma (5 papers, 2015 to 2024). "As BRAF, TERT, HLA-G, and microRNAs have been individually associated with papillary thyroid carcinoma (PTC), we aimed to evaluate the individual and collaborative role of these markers in PTC in the same patient cohort." (PMID 37569841, 2023). "Human leukocyte antigen (HLA)-G is an immune checkpoint molecule that is highly expressed in papillary thyroid carcinoma (PTC)." (PMID 37629044, 2023).
parasite infection (5 papers, 2008 to 2022). "Thus, we speculate that the key immunomodulatory role of the cytokines TGF-β and IL-10 and the essential regulation of T cells including Treg cells by TGF-β might initially be linked molecularly at least during the early phase of parasite infections with HLA-G levels." (PMID 35204759, 2022). "It is known that cytokines such as IL-10 can induce HLA-G expression by affecting mRNA transcripts and protein synthesis by human monocytes and trophoblasts, thus having a significant impact on parasitic infections." (PMID 29059176, 2017).
adenoma (4 papers, 2008 to 2025). A neoplasm arising from the epithelium. "In one of these cases, however, sHLA-G levels in benign colorectal diseases (i.e., hyperplastic polyps, adenomas and IBD) significantly differed from healthy controls as well, indicating that for HLA-G non-malignant disease controls are also highly important." (PMID 33353014, 2020). "For instance, a research group found that 65% of CRC tissue samples had HLA-G expression, while no expression was detected in normal colorectal tissues or benign adenomas." (PMID 41234446, 2025).
adenomyosis (4 papers, 2018 to 2024). The growth of endometrial tissue inside the muscular wall of the uterine corpus. "Ithas been shown that patients with adenomyosis have bothHLA-DR and HLA-G expression in eutopic and ectopicendometrium." (PMID 29043703, 2018). "In addition, HLA-G was expressed in both in situ and ectopic endometria of patients with adenomyosis, and HLA-G expression was also detected in ectopic endometrial lesions during menstruation." (PMID 35720413, 2022). "Furthermore, alterations in immune-modulating proteins like HLA-G, which are involved in immune tolerance, have been noted in adenomyosis, potentially impairing the immune system’s ability to differentiate self from non-self and facilitating the coexistence of adenomyosis with autoimmune conditions." (PMID 39518312, 2024).
allergic asthma (4 papers, 2016 to 2023). A asthma with a basis in a pathological type I hypersensitivity reaction. "We also identified SNP rs1063320 in the HLA-G gene in patients from the general Italian population; this deserves additional examination to better understand its role in the allergic asthma phenotype." (PMID 37373658, 2023). "HLA-G genetic polymorphisms confer susceptibility to allergic asthma development and high levels of soluble HLA-G molecules are found in plasma and bronchoalveolar lavage fluid of patients with allergic asthma correlating with allergen-specific IgE levels." (PMID 35082780, 2021).
allergic rhinitis (4 papers, 2016 to 2023). Inflammation of the nasal mucous membranes caused by an IgE-mediated response to external allergens. "Elevated levels of soluble HLA-G molecules are detected in serum of patients with allergic rhinitis correlating with allergen-specific IgE levels, clinical severity, drug consumption and response to allergen-specific immunotherapy." (PMID 35082780, 2021). "Elevated levels of soluble HLA-G (sHLA-G) molecules are detected in serum of patients with allergic rhinitis to seasonal and perennial allergens and correlate with allergen-specific IgE levels, clinical severity, drug consumption, and response to allergen-specific immunotherapy." (PMID 27413762, 2016).
Arthritis (4 papers, 2010 to 2015). Inflammation of a joint. "In mice, recombinant sHLA-G and synthetic HLA-G molecules have been shown to inhibit the early stages of arthritis in a rheumatoid arthritis disease model and to significantly prolong the acceptance of skin grafts." (PMID 24860568, 2014). "In addition, the HLA-G 3741_3754 14-base pair insertion allele was found to occur significantly more frequently in BD patients with ocular, arthritis, and CNS symptoms than in controls, and this insertion was found to be related to the lower serum level of HLA-G." (PMID 20573271, 2010).
Chagas disease (4 papers, 2014 to 2022). A parasitic infection caused by Trypanosoma cruzi. "In terms of Chagas disease susceptibility, HLA-G 3′UTR alleles/genotypes/haplotypes exhibited differential frequencies in infected/diseased patients when compared to only infected patients and healthy controls." (PMID 25688175, 2015). "Chagas disease patients exhibited differential HLA-G 3′UTR susceptibility allele/genotype/haplotype patterns, according to the major clinical variant (digestive/cardiac/mixed/indeterminate)." (PMID 25688175, 2015). "For instance, the decreased expression of HLA-G (placentas of P. falciparum-infected mothers or heart and colonic specimens of Chagas disease) has been associated with morbidity of the chronic parasitic infection." (PMID 25699038, 2015). "We evaluated the HLA-G 3′ untranslated region (3′UTR) polymorphic sites (associated with mRNA stability and target for microRNA binding) and HLA-G tissue expression (heart, colon, and esophagus) in patients presenting Chagas disease, stratified according to the major clinical variants." (PMID 25688175, 2015). "When HLA-G 3′UTR polymorphic sites were considered as haplotypes, decreased UTR-4 and UTR-7 frequencies were associated with the clinically detectable Chagas disease and with the digestive form, respectively." (PMID 25688175, 2015). "Interestingly, a decreased membrane-bound HLA-G has been detected in the placenta of patients infected by P. falciparum and in the heart and colon of Chagas disease patients." (PMID 35204759, 2022). "The HLA-G immunolabeling in esophagus of Chagas patients with esophagomegaly was closely similar to that observed for individuals without Chagas disease." (PMID 25688175, 2015). "Of note, HLA-G, a non-classical class I major histocompatibility complex molecule playing a tolerogenic role in innate and adaptive responses was not expressed in inflammatory cell infiltrates of chronic Chagas disease patients, while it was expressed by cardiomyocytes in GCM." (PMID 25144227, 2014).
Hepatitis (4 papers, 2015 to 2024). Inflammation of the liver. "In addition, the few studies conducted on hepatitis and parasitic disorders indicate that HLA-G may contribute to disease pathogenesis." (PMID 25699038, 2015). "The higher expression of HLA-G may contribute to liver transplant tolerance and successful pregnancy, while AIH patients, notably patients with severe liver inflammation, revealed significantly lower soluble HLA-G levels." (PMID 39273280, 2024).
Hodgkins lymphoma (4 papers, 2012 to 2020). A heterogeneous group of malignant lymphoid neoplasms of B-cell origin characterized histologically by the presence of Hodgkin and Reed-Sternberg (HRS) cells in the vast majority of cases. "In this study, we tested whether polymorphisms in human leukocyte antigen G (HLA-G) were associated with event-free survival (EFS) in pediatric Hodgkin's lymphoma (HL)." (PMID 29285306, 2017). "Expression of HLA-G in classical Hodgkin lymphoma was also independently determined by the groups of Diepstra and Caocci." (PMID 32922387, 2020). "They both determined a relatively high expression of HLA-G (>54% of expressing tumor cells) in the Reed-Stenberg cells, with particular higher expression in nodular sclerosis." (PMID 32922387, 2020).